EPCAM (epithelial cell adhesion molecule)
Diseases named in the same sentence as EPCAM in open-access papers (continued):
Sharing a sentence is not in itself a finding about the gene and the disease.
colon carcinoma (continued). "Interestingly, the increased regulated intramembranous proteolysis of EpCAM resulting in release of its cytoplasmic domain, Ep-ICD in colon carcinoma and its subsequent translocation to the nucleus has been demonstrated to trigger oncogenic signaling." (PMID 27421772, 2016). "No CTCs were detected from lung samples by CellSearch, which may be due their reduced expression of EpCAM, and supports the fact that CellSearch is only FDA approved for breast, prostate, and colon cancer blood samples." (PMID 26863573, 2016). "Further, incubation of the EpCAM+ colon carcinoma cell line DLD-1 with anti-EpCAM:CD40L showed a strong anti-CD40L fluorescence signal that was completely inhibited by pre-incubation with an epitope-competing EpCAM-blocking antibody." (PMID 24741998, 2014). "The increased regulated intramembrane proteolysis of EpCAM resulting in release of its cytoplasmic domain, Ep-ICD, and its subsequent translocation to the nucleus has been demonstrated to trigger oncogenic signalling in colon carcinoma." (PMID 25265904, 2014). "For example, treatment of HCT116 colon cancer cells with papain (enzyme used for dissociation of some solid tumors) reduced the detection of CD44 from 93.4% down to 0.5% of cells while EpCAM and CD133 (AC133) were not significantly affected." (PMID 23308131, 2013). "Although an antibody against EpCAM has successfully been used as an adjuvant therapy in colon cancer, this therapy has never gained wide-spread use." (PMID 22590529, 2012). "It is less likely that a known marker for colon cancer stem cells, such as CD44, CD166, EpCAM, and Lgr5, has the potential just like Pten-related pathway in leukemia, which could distinguish hematopoietic stem cells from leukemia-initiating cells." (PMID 19583834, 2009). "In addition, we demonstrate that CD133+ cell groups were CK20− and EpCAM+, which is in accordance with previous studies that characterised the phenotype of CD133+ colon cancer cells using tumour cell suspensions." (PMID 18781171, 2008). "In colon cancer, CD133+ cells were shown to be devoid of the intestinal epithelial differentiation marker cytokeratin 20 (CK20), whereas they keep positivity for the epithelial adhesion molecule EpCAM." (PMID 18781171, 2008). "Finally, we show that the combined treatment of an anti-EpCAM neutralizing antibody (EpAb2-6) and an HGFR inhibitor (crizotinib) significantly inhibits tumor progression and prolongs survival in metastatic and orthotopic animal models of colon cancer." (PMID 37543570, 2023). "Similarly, cancer-related markers, such as ROR1 or EpCAM, which are overexpressed in PCa, but also in other carcinomas such as colon cancer, were not able to distinguish between the benign and malignant changes in the prostate." (PMID 35740652, 2022). "This may be because the group of determinant CTCs has not been precisely identified, as exemplified by the fact that only vimentin-positive CTCs were related to patient outcomes rather than EpCAM-positive CTCs in colon cancers." (PMID 35646680, 2022). "Additionally, EpCAM has been reported to be an epithelial cell-specific marker, which is highly expressed in breast, prostate, and colon cancers but not RCC." (PMID 31416266, 2019). "Small metastases in mice with colon carcinoma were EpCAM-negative." (PMID 23110550, 2012). "Recombinant extracellular domain of EpCAM induces EGFR phosphorylation and MAPK and Akt activation in the absence of EGF in colon cancer HCT116, Colo205 and HT-29 cells and in mesenchymal stem cells." (PMID 39594667, 2024). "Using a colon cancer xenograft model, they demonstrated that EpAb2-6 induced CRC cell death by inhibiting EpCAM signaling rather than by acting through the ADCC or CDC." (PMID 33154781, 2020). "This unattached phenotype suggests a defect in cell adhesion, and in the panel of colon cancer lines only NCI-H716 and RKO cells lacked both EPCAM and CDH1 expression." (PMID 24968263, 2014).
colon carcinoma (continued). "Furthermore, we selected HT29, an EpCAM+ colon cancer line and the metastatic cell lines LNCaP and PC3, positive and negative for EpCAM, respectively." (PMID 34155195, 2021). "Regarding to this fact, recent studies have demonstrated that, at the time of surgery, the detection of CTCs with CK20 by real-time polymerase chain reaction (RT-PCR) without using anti-EpCAM immunoisolation, is an independent prognostic factor for OS and DFS in colon cancer patients." (PMID 28608814, 2017).
hepatocellular carcinoma (178 papers, 2009 to 2026). A malignant tumor that arises from hepatocytes. "In a recent study, researchers identified a high-risk tumor subtype of hepatocellular carcinoma using intratumoral EpCAM+ cancer stem cell." (PMID 36910604, 2023). "In the Huh-7 hepatoma cell line, selection of EpCAM-positive cells has been associated with enhancement of in vivo tumorigenicity and in vitro characteristics associated with aggressiveness, such as anchorage independent growth." (PMID 28152020, 2017). "We observed that the elevated expression of both ZFX and epithelial cell adhesion molecule (EpCAM) was associated with aggressive clinicopathological features and indicated poor prognosis in patients with hepatocellular carcinoma (HCC)." (PMID 28156061, 2017). "Herein, we show that in vivo passage has led to a hepatocellular carcinoma cell line with enhanced tumorigenicity and EpCAM expression, hallmark characteristics of tumor initiating cells (TIC)." (PMID 28152020, 2017). "It has indeed been shown that EpCAM may induce a CSC-like gene signature in HBV-associated hepatocellular carcinomas." (PMID 30116994, 2018). "Concurrently, expression of HBx protein of HBV in HepG2 hepatoma cells greatly enhanced the abundance of the pluripotency transcription factors such as Oct-4, Nanog, and Klf-4, as well as the “stemness”-associated markers EpCAM and β-catenin." (PMID 26042045, 2015). "Hepatitis B virus (HBV) encoded X antigen (HBVx) was reported to activate stemness associated factors OCT-4, NANOG, β-catenin, KLF 4, and EpCAM as well as induce cell migration and sphere formation in hepatocellular carcinomas (HCC)." (PMID 37954619, 2023). "In addition, in a study performed with PCR and FACS, high pre-resection levels of both epithelial cell adhesion molecule (EpCAM)-positive CTCs and circulating Tregs correlated with a higher risk of post-resection recurrence and metastasis in hepatocellular carcinoma patients." (PMID 30200242, 2018). "Human fibroblast growth factor 19 (FGF19), its receptor (FGFR4) and EpCAM play an important role in cell proliferation, differentiation, motility, and overexpression have been linked to hepatocellular carcinoma (HCC)." (PMID 27447573, 2016). "A similar study showed that HOXB7 was highly expressed in hepatocellular carcinoma, where it promoted cell proliferation, upregulated cancer stem cell markers EPCAM and NANOG, enhanced c-Myc and Slug expression, and promoted tumor growth." (PMID 41040515, 2025). "In alignment with our findings, other studies reported the positive correlation of EpCAM expression with Ki-67 in gastric and hepatocellular carcinoma." (PMID 40806559, 2025). "On coculturing normal fibroblasts with EpCAM-positive human hepatoma cells, the latter were transformed into CD90-positive CSCs at high probability." (PMID 40253402, 2025). "In contrast, limited expression of EpCAM is found in renal clear cell carcinoma, hepatocellular carcinoma, and glioma." (PMID 38791091, 2024). "EpCAM staining was the lowest in hepatocellular carcinomas, adrenocortical tumors, renal cell neoplasms, and in poorly differentiated carcinomas." (PMID 38786342, 2024). "EpCAM has therefore been suggested as a tool for the distinction of hepatocellular carcinomas and malignant mesotheliomas from their differential diagnoses." (PMID 38786342, 2024). "A recent study revealed that by inhibiting lysine demethylase 2A (KDM2A)-mediated demethylation of H3K26m2, ZHX2 downregulates the expression of stemness genes, including EPCAM, in hepatocellular carcinoma stem cells." (PMID 38791091, 2024). "The positivity rate was lower for EpCAM in mesotheliomas, hepatocellular carcinomas, very poorly differentiated tumors (anaplastic thyroid cancer, sarcomatoid urothelial cancer), and—to a lesser extent—in squamous cell carcinomas." (PMID 38786342, 2024).
hepatocellular carcinoma (continued). "In this prospective pilot study, we analyzed the presence of EpCAM+ CTCs using the IsoFlux system in the peripheral blood of 37 patients with hepatocellular carcinoma undergoing transarterial chemoembolization (TACE)." (PMID 36768881, 2023). "Inhibition of mTORC2 leads to a reduction in the expression of liver CSC markers (epithelial cell adhesion molecule, EpCAM) in hepatocellular carcinoma stem cells." (PMID 35558559, 2022). "Stemness of CD133+EPCAM+ hepatocellular carcinoma cells ensures cancer resistance to apoptosis,which is a challenge to current liver cancer treatments." (PMID 35820920, 2022). "EpCAM has been demonstrated to be one of the targets of chemoresistance in human hepatocellular carcinoma cell lines." (PMID 36397165, 2022). "The epithelial cell adhesion molecule (EpCAM) and Thy-1 cell surface antigen (CD90) have been implicated as cancer stem cell (CSC) markers in hepatocellular carcinoma (HCC)." (PMID 35454789, 2022). "EpCAM was found to be one of the Wnt-β-catenin signaling direct transcription target in normal human hepatocytes and hepatoma cells." (PMID 34306031, 2021). "In hepatocellular carcinoma, EpCAM+ CD133+ cells demonstrated elevated colony formation ability, expression of stem cell related genes and chemoresistance compared to EpCAM- CD133+ cells." (PMID 33889547, 2021). "BMP9‐ID1 signaling plays a pivotal role in promoting the cancer stem cell properties of EpCAM+ hepatocellular carcinoma (HCC) cells by activating Wnt/β‐catenin signaling." (PMID 33834612, 2021). "Some epithelial cancers, however, demonstrated low EpCAM expression, including squamous cell cancers, hepatocellular carcinomas, clear cell renal carcinoma, and urothelial cancers, while some sarcomas have shown elevated EpCAM expression." (PMID 34209658, 2021). "The epithelial cell adhesion molecule (EpCAM, CD326) is expressed on CSCs in various tumor types including colon and hepatocellular cancers." (PMID 32849491, 2020). "Flow-cytometry analysis showed that EpCAM+ HCC cells was reduced in miR-96 knockdown hepatoma cells." (PMID 33046975, 2020). "The WNT signalling pathway transcriptionally regulates EpCAM expression in hepatocellular carcinoma via its downstream effector TCF/Beta-catenin complex." (PMID 32046162, 2020). "Data from systematic analyses suggest that EpCAM expression is essential for all human adenocarcinomas, including specific types of squamous cell carcinoma, retinoblastoma, and hepatocellular carcinoma." (PMID 32466488, 2020). "In the presence of the EpCAM expressing hepatocellular carcinomas cell line of HepG2, the specific immune recognition (Anti-EpCAM/EpCAM) led to an obvious change of the electron transfer ability." (PMID 31010258, 2019). "Studies have showed that EpCAM-positive hepatocellular carcinoma cells possess CSCs features, such as tumor initiating capacity and invasive ability." (PMID 30691509, 2019). "A recent study has shown that 4-MU treatment significantly reduced expression of CD44, CD133, CD90 and EpCAM in hepatic carcinoma cells in vitro." (PMID 31443261, 2019). "Next, we found that the proportion of EpCAM in miR-28-5p overexpression hepatoma cells was downregulated." (PMID 31885628, 2019). "Owing to the fact that hepatocellular carcinoma is the most common primary liver malignancy, we chose the HepG2 with positively-expressed EpCAM cell line as the target cells." (PMID 31010258, 2019). "A study of hepatocellular carcinoma showed that activation of the Wnt/β-catenin pathway upregulates EpCAM expression." (PMID 29305578, 2018). "Previously, we found that EpCAM was up-regulated in hepatocellular carcinoma cells after treatment with chemotherapeutic agents, implying a critical role of EpCAM in cell survival." (PMID 30116994, 2018). "The epithelial cell adhesion molecule (EpCAM) has been proposed as a marker for cancer stem cells in human hepatocellular carcinoma (HCC) as well as in the development of novel target therapies." (PMID 30112355, 2018).
hepatocellular carcinoma (continued). "Lidamycin (an enediyne anticancer antibiotic) was able to reduce tumor initiating cells of hepatocellular carcinoma reducing stem cell markers expression, such as EpCAM, by inhibiting Wnt/β-catenin pathway activation." (PMID 30112355, 2018). "Moreover, a study recently demonstrated that EpCAM expression in hepatocellular carcinoma cell lines was associated with chemoresistence, in favor of the recurrence for HCC patients." (PMID 28572700, 2017). "To further explore the potential role of ZFX in regulating the stem‐like properties of EpCAM+ liver CSCs, we used a lentivirus‐based knockdown approach to establish shZFX‐stable transfectants of hepatoma cells (Huh7 and MHCC‐97L)." (PMID 28156061, 2017). "TGM2, a candidate marker for hepatocellular carcinoma and EpCAM (epithelial cell adhesion molecule) were highly expressed in Hep3B-EVs and HepG2-EVs, but only faintly in HuH7-EVs and HuH6-EVs." (PMID 29137313, 2017). "The epithelial cell adhesion molecule (EpCAM) is a type I transmembrane glycoprotein that is regarded as one of the markers for tumor initiating cells (TIC) in human hepatocellular carcinoma (HCC)." (PMID 28903370, 2017). "An aptamer binding to epithelial cell adhesion molecule (EpCAM) was employed by Babaei and colleagues for hepatocellular carcinoma targeting in vitro and in vivo." (PMID 28737672, 2017). "This is the first study to elucidate FGF19/FGFR4 signaling in favor of HCC cells developing as indicated by increased EpCAM within the carcinogenesis sequence from fatty liver to hepatocellular carcinoma." (PMID 27447573, 2016). "SALL4 is part of the Wnt signalling pathway and regulates the stemness of EPCAM-positive hepatocellular carcinomas." (PMID 27534621, 2016). "In this regard, ALDH+/CD133+ cells in colon cancer and EpCAM+/CD133+ CSCs from hepatocellular cancer demonstrate increased activation of IL-6/STAT3 activity and causal association in CSCs niche expansion." (PMID 31656694, 2016). "In the current study, by using hepatoma sphere cells and the sorted hepatoma EpCAM+ cells, we evaluated the inhibitory effect of WM130 on HCC CSCs." (PMID 27783993, 2016). "In our study, we sought to construct a novel RNAi vector simultaneously expressing VEGFR2, CCR1, and EpCAM shRNA cassettes and test its effects on hepatoma cell lines." (PMID 27221035, 2016). "This study helps to elucidate a relationship between FGF19 and its respective receptor FGFR4 in the promotion of hepatic stem cells as indicated by increased EpCAM within the carcinogenesis sequence of fatty liver to hepatocellular carcinoma in the specimens." (PMID 27447573, 2016). "Pathological changes of the liver are accompanied by a strong re-expression of EpCAM, for example in hepatocellular carcinomas, where EpCAM serves as a marker for cancer stem cells." (PMID 25477371, 2015). "Compared with epithelial CTCs detected by the conventional markers EpCAM and cytokeratin, the high rates of EMT-positive CTCs were associated with prognosis in patients with hepatocellular carcinoma." (PMID 25986923, 2015). "MTT assay confirmed potent reduction in EpCAM-positive HHCC (human hepatocellular carcinoma) cell viability (IC50 50 pM)." (PMID 25960617, 2015). "Previous studies reported that VB4-845, an immunotox in targeting EpCAM, showed potent cytotoxicity and was significantly effective in combination with 5-FU in hepatocellular carcinoma cells." (PMID 25019346, 2014). "Previous studies on miR-181 family in hepatocellular carcinoma showed a regulatory link between miR-181 family and EpCAM positive cancer cells." (PMID 25502397, 2014). "Recent studies have revealed that EPCAM is over-expressed in a variety of human cancers, including lung, esophagus, gastric, breast, colorectal, and hepatocellular carcinomas." (PMID 24718422, 2014). "Many reports suggest that epithelial cell adhesion molecule (EpCAM) is a useful marker for cancer stem cells in hepatocellular carcinoma (HCC)." (PMID 24696843, 2014).